EGFR (epidermal growth factor receptor)
Diseases named in the same sentence as EGFR in open-access papers (continued):
Sharing a sentence is not in itself a finding about the gene and the disease.
ovarian carcinoma (continued). "PTAFR has been shown to activate the EGFR and ERK signaling pathways in ovarian cancer cells, therefore potentially contributing to cancer progression." (PMID 35625966, 2022). "Results exhibited positive correlations of MYC, EGFR, and CCND1 with overall survival of ovarian cancer patients after chemotherapy." (PMID 35739532, 2022). "The depletion of PRP4K also enhances both Yap and epidermal growth factor receptor (EGFR) signaling, the latter promoting anoikis resistance in breast and ovarian cancer." (PMID 35281802, 2022). "By loading anti-HER2 or anti-EGFR bispecific antibodies, CD19-CAR-T and activated T cells showed comparable specific cytotoxicity against ovarian cancer cells." (PMID 36275669, 2022). "An increase in the expression level of mRNA and protein in women with ovarian cancer was observed for KRAS, c-FOS, and EGFR." (PMID 35807169, 2022). "miR-7 expression was shown to be decreased in highly metastatic epithelial ovarian cancer (EOC) cell lines and metastatic tissues, whereas EGFR expression was positively correlated with metastasis in both EOC patients and cell lines." (PMID 36012357, 2022). "Upstream regulation of NF-κB is mediated through epidermal growth factor receptor (EGFR), a tyrosine kinase receptor that is increased in 70% of ovarian cancers." (PMID 36531159, 2022). "Combined with results of PPI analyses and TCGA database, MYC, EGFR, and CCND1 were determined to be the key genes correlated with the chemoresistance affected by CAFs in ovarian cancer." (PMID 35739532, 2022). "In general, estrogen stimulation of ovarian cancer cell proliferation requires both GPER- and ER-mediated complete epidermal growth factor receptor (EGFR) signaling." (PMID 33669960, 2021). "In this study, we found that high EGFR and IL-6-STAT3 expression predicted a worse survival rate in ovarian cancer patients." (PMID 34369236, 2021). "We found that high mRNA expression of EGFR was related to worse OS and PFS in all ovarian cancer patients." (PMID 34369236, 2021). "Our results identify an epigenetic mechanism among miR-146b, EGFR and the IL-6-STAT3 pathway, thus adding to our understanding of how the IL-6-STAT3 pathway is regulated in ovarian cancer." (PMID 34369236, 2021). "To further investigate the role of the EGFR and IL-6-STAT3 pathways, we analysed the expression levels of these molecules in ovarian cancer." (PMID 34369236, 2021). "Epidermal growth factor receptor (EGFR) signalling and the interleukin-6 (IL-6)/signal transducer and activator of transcription 3 (STAT3) are aberrantly activated in ovarian cancer." (PMID 34369236, 2021). "Taken together, these findings indicated, for the first time, that miR-146b blocks both the EGFR and IL-6-STAT3 pathways in ovarian cancer cells." (PMID 34369236, 2021). "A concomitant significant increase in EGFR expression and upregulation of MEK-ERK signaling was observed in adherent 3D ovarian cancer nodules grown under continuous flow and treated with carboplatin." (PMID 34503128, 2021). "Previous studies have confirmed that HE4 plays an important role in the metastasis and adhesion of ovarian cancer cells, with low levels of HE4 preventing the activation of ERK and EGFR in ovarian cancer cells." (PMID 34107979, 2021). "In ovarian cancer cells SKOV3 and OVCAR3, EGFR activation also increased SNAIL mRNA levels, which required EGF-induced H2O2 production and p38 MAPK activation." (PMID 35127732, 2021). "For example, CAF-derived TGF-α promotes the metastatic colonization of ovarian cancer cells via activation of AKT, epidermal growth factor receptor (EGFR), and extracellular signal-regulated kinase (ERK)-1/2 signaling pathways." (PMID 34356110, 2021).
ovarian carcinoma (continued). "Currently, molecular targeted drugs, targeting the inhibition of vascular endothelial growth factor (VEGF), epidermal growth factor receptor (EGFR), platelet derived factor receptor (PDGFR) and so on, shed light on the treatment of ovarian cancer." (PMID 34294689, 2021). "Taken together, these findings demonstrated that the EGFR and IL-6-STAT3 pathways have a prognostic value in ovarian cancer." (PMID 34369236, 2021). "In the case of I3C, experimental studies have shown that through its active metabolites (3,3’-diindolylmethane), it blocks the epidermal growth factor receptor (EGFR), whose overexpression is observed in ovarian cancer, among others." (PMID 33530651, 2021). "A potential target for ovarian cancer is the marker human epidermal growth factor receptor-2 (HER2), a member of the epidermal growth factor receptor (EGFR) family of transmembrane receptor tyrosine kinases." (PMID 34439149, 2021). "Previous studies have reported that EGFR is overexpressed and phospho-ERK1/2 is elevated in 35–70% of human ovarian cancer samples." (PMID 32231055, 2020). "Studies have pointed out that PAK4 modulates ovarian cancer tumor progression via c-Src/ERK1/2 and EGFR/MMP2 signal pathway." (PMID 32549768, 2020). "The epidermal growth factor receptor (EGFR) is critical for proliferation and tumorigenesis in ovarian cancer, with it being reported that EGF activates TRPC3/4/5, thus prompting Ca2+ inflow in HEK293 cells (human embryonic kidney 293 cells)." (PMID 32785177, 2020). "The inhibition of the EGFR pathway inhibited c-fos and ERK activation, indicating that in ovarian cancer cells, the GPER1/EGFR signaling relies on ERα expression." (PMID 32580290, 2020). "The ovarian cancer cells stimulated by EGF of TAMs underwent EMT through upregulation of N-cadherin and vimentin, activation of EGFR/ERK signaling, and downregulation of IncRNA inhibiting metastasis (LIMT) expression." (PMID 32283687, 2020). "MiR-491-5p induces cell apoptosis in ovarian cancer through direct inhibition of both BCL-XL and EGFR." (PMID 32808668, 2020). "Ongoing clinical trials in ovarian cancer are evaluating inhibitors of multiple molecular pathways such as PI3K/AKT, the mTOR pathway, angiogenesis, the MAPK pathway, and the HER/EGFR pathway." (PMID 33256002, 2020). "Related studies about sphingolipid, EGFR tyrosine kinase inhibitor, cellular senescence, PI3K/AKT network and metabolism of lipids in ovarian cancer were found." (PMID 32192517, 2020). "Double anti-tyrosine kinase inhibitor AEE788, which is able to block EGFR and VEGFR simultaneously, was already tested in the orthotropic mouse model of ovarian cancer." (PMID 31540126, 2019). "EGFR signaling stimulates the expression of LSD1 in ovarian cancer cells, and EGFR-LSD1 pathway plays a mechanistic role in the cell migratory activity of EGFR, presumably, via modifying the methylation status of its putative targets." (PMID 31426393, 2019). "In our own work we find phosphorylation of the intracellular domain of EGFR as well as phosphorylation of AKT and ERK upon treatment of ovarian cancer cells with SPINK1, consistent with activation of EGFR downstream pathways." (PMID 30778387, 2019). "There is some evidence to suggest a role of EGFR signaling in upregulating DNMT activity and DNA methylation in ovarian cancer cells." (PMID 31426393, 2019). "MiR-3613 was recently identified to overexpress in ovarian cancers and down-regulate PTEN, a regulator of PI3K-Akt signaling downstream of EGFR." (PMID 31296175, 2019). "For example, engagement of EGFR and HER3 signaling by HB-EGF and heregulin, respectively, activates YAP1 transcription regulator which in-turn, increases the expression of EGFR and HER3 as well as several of their ligands in ovarian cancer cells." (PMID 31426393, 2019).
ovarian carcinoma (continued). "In addition, our previous studies revealed that most ovarian cancer cell lines show functional resistance to the anti-EGFR antibody cetuximab which could not be resolved by the simultaneous addition of the corresponding anti-EGFR TKIs." (PMID 31546690, 2019). "Epidermal growth factor receptor (EGFR, ErbB1, HER1) has been described as overexpressed in ovarian epithelial cancer of all histologic subtypes." (PMID 32039018, 2019). "At cut off value of >5% of tumours with positive staining, EGFR and HER-2 expression was detected in 62% and 93% of the ovarian cancer cases respectively." (PMID 29731973, 2018). "Our results showed that CHAG suppressed the migration and invasion of ovarian cancer cells, and delayed the development OC implantation tumor through blocking EGF-stimulated activation of EGFR and its downstream signal transduction." (PMID 29510732, 2018). "The expression of EGFR, HER-2, HER-3 and HER-4 reported in the literature for ovarian cancer exhibits wide variation ranging from 9–90%, 6.4–52%, 16–69%, and 65–90% of the cases examined respectively, with EGFRvIII expression being rare." (PMID 29731973, 2018). "It was recently demonstrated that EGFR inhibitors attenuated the promoting effect of CTHRC1 on epithelial ovarian cancer invasion and that phosphorylation of EGFR and ERK1/2 was reduced in CTHRC1-silenced ovarian cancer cells." (PMID 28645305, 2017). "Our data also demonstrated that miR-34c-5p was able to repress ovarian cancer stemness and drug resistance via targeting AREG-mediated EGFR-ERK pathway." (PMID 28459431, 2017). "Interfering RNA-induced stable inhibition of NRF2 in ovarian carcinoma SKOV3 and renal carcinoma A498 reduced the levels of c-MET and EGFR." (PMID 29291022, 2017). "In ovarian cancer cells, activation of GPER promotes cell survival via the transactivation of EGFR and cross talk with the PI3K/AKT signaling pathway." (PMID 28439256, 2017). "There may be room for applications of yet untested EGFR modulating drugs or strategies in ovarian cancer patients, but this will likely require a different approach for patient stratification, as current investigation shows that EGFR staining is not consistently associated with tumor response." (PMID 28740577, 2017). "Other immunohistochemical markers downstream of EGFR signaling pathways such as pAKT, pERK (also known as pMAPK), or pSTAT3 could potentially be more useful as prognostic markers and might also help to stratify ovarian cancer patient populations for treatment with TKIs." (PMID 28740577, 2017). "This has already been demonstrated in former studies using various high EGFR expressing cell lines such as HuH7 liver cancer cells and SKOV-3 ovarian carcinoma cells." (PMID 29190908, 2017). "Next, we analyzed the mRNA levels of the different STs, namely, ST3GalI-VI in response to EGFR inhibitor treatments (erlotinib, lapatinib, ZD-6474, TKI258) in different ovarian cancer cell lines listed in the Cancer Cell Line Encyclopedia (CCLE) database." (PMID 28423672, 2017). "It is worthy to note that some of the genes selected by the three methods (e.g., NPY, COL5A1, EGFR, and FBL1) have been already reported in literature where an analysis of subnetwork signatures in ovarian cancer based on Cox model is presented." (PMID 27378931, 2016). "In contrast, EGFR contributed to an enhanced production of cancer chemokines such as IL-8 and CXCL-1 in ovarian cancer cells." (PMID 27708225, 2016). "Furthermore, some studies have shown that UCA1 was related to drug resistance in some malignancies, including ovarian cancer, bladder cancer and EGFR-mutant NSCLC, suggesting that UCA1 could be applied as a biomarker for monitoring the efficacy of chemotherapy." (PMID 27517147, 2016).
ovarian carcinoma (continued). "Other interesting markers are MUC1, EGFR and CD142, which are all highly related to cancer, particularly ovarian cancer." (PMID 28936249, 2016). "Further on, evidence suggest that αvβ3 also regulates epidermal growth factor receptor (EGFR) promoter activity and influences co-clustering of the receptor on the ovarian cancer cell surface." (PMID 27929432, 2016). "In our recent study, potentiating NF-κB activation through EGFR-transactivated Akt augmented proinflammatory chemokines CXCL1/2, contributing to CXCR2-driven ovarian cancer progression." (PMID 27723802, 2016). "To determine the relationship between LSD1 and EGFR, we analyzed the protein expression of LSD1 and EGFR in the SKOV3, HO8910, and 3AO ovarian cancer cell lines." (PMID 26489763, 2015). "We found that inhibition of the EGFR attenuates cisplatin induced increases in DNMT activity, prevents increased DNA methylation and also diminishes platinum resistance in ovarian cancer cells." (PMID 26351843, 2015). "Serous (69.5 %) and mucinous (11.3 %) ovarian cancer had high proportions of low BRAF expression, while serous (63.6 %) and endometrioid (13.6 %) ovarian cancer exhibited high EGFR expression." (PMID 26490766, 2015). "Ovarian cancer cells harbor COX-1 and COX-2 enzymes and the main metabolic intermediary, COX-2, can regulate cell migration via the intracellular activation of EGFR." (PMID 26558612, 2015). "Furthermore, EGFR inhibition may be an effective strategy at attenuating the development of platinum resistance thereby enhancing the effectiveness of chemotherapeutic treatment in ovarian cancer." (PMID 26351843, 2015). "Our model supported notion that the four molecules in the EGFR/HER2/KRAS/BRAF signaling pathway also produce the synergic effect, exerting their own effect on ovarian cancer progression." (PMID 26490766, 2015). "We previously showed that activation of the EGFR in ovarian cancer cells increases DNMT activity and over long term EGFR activation can lead to increased DNA methylation as well as decreased sensitivity to cisplatin." (PMID 26351843, 2015). "Overall, these results support a consistent synergistic effect of EGFR and JAK/STAT3 inhibition on ovarian cancer cell growth and survival both in vitro and in vivo and a potential role for multiple survival pathways in this effect." (PMID 25928246, 2015). "Following HE4 gene knockout, the phosphorylation levels of EGFR and Erk1/2 in ovarian cancer were affected; when HE4 was added to the cell culture, the phosphorylation levels of EGFR and Erk1/2 were restored." (PMID 26539494, 2015). "Both epidermal growth factor receptor (EGFR) and fibroblast growth factor receptor 1 (FGFR1) are overexpressed in the majority of human tumors, including ovarian cancer." (PMID 25919378, 2015). "EGFR is one of the main kinases involved in activation of a number of downstream survival pathways, such as ERK, AKT and SRC, in ovarian cancer cells." (PMID 25928246, 2015). "We next investigated the signaling pathway downstream of activated EGFR and PAFR in ovarian cancer cells to elucidate the mechanisms involved in EGF-induced PAF production." (PMID 24721622, 2014). "Epidermal growth factor receptor (EGFR) is involved in the development and progression of several human cancers, including ovarian cancer." (PMID 24886678, 2014). "We previously identified platelet-activating factor receptor (PAFR) as being overexpressed in ovarian cancer and found that its ligand PAF evoked EGFR phosphorylation." (PMID 24886678, 2014). "Our data demonstrated the involvement of the EGFR/ AKT and EGFR/ERK1/2 pathways in the miR-7 reversed EMT in ovarian cancer cells." (PMID 24816687, 2014). "In the present study, we demonstrated that PAF transactivates EGFR through PAFR in both time- and dose-dependent manners in the SKOV-3 ovarian cancer cells." (PMID 25261977, 2014).
ovarian carcinoma (continued). "The results suggest that in SKOV-3 ovarian cancer cells, PAF transactivates EGFR and downstream ERK pathways, thus diversifying the GPCR-mediated signal." (PMID 25261977, 2014). "EGFR gene family members have been shown to be widely expressed in various human cancers, including breast, head and neck, NSCLC and ovarian cancers." (PMID 25202368, 2014). "Our previous study reported that the PAFR ligand PAF can activate phospho-EGFR and induce proliferation and invasion in ovarian cancer, and the results of the present study show that the PAFR antagonist WEB2086 can inhibit EGFR activation." (PMID 24886678, 2014). "We previously identified platelet-activating factor receptor (PAFR) as being overexpressed in ovarian cancer and found that its ligand PAF evoked EGFR phosphorylation using the phospho-antibody microarray." (PMID 25261977, 2014). "The combined usage of selective inhibitors of PAFR and EGFR, such as WEB2086 and AG1478, represents a promising strategy for the treatment of ovarian cancer." (PMID 24886678, 2014). "In this study, we demonstrate that EGF stimulates the phosphorylation of PLCβ, which can be blocked by the EGFR inhibitor AG1478, suggesting that the crosstalk occurs bidirectionally between EGFR and PAFR in ovarian cancer cell lines." (PMID 24721622, 2014). "In the present study, we demonstrated that PAFR is capable of stimulating the activation of EGFR and ERK1/2 in ovarian cancer cells endogenously expressing PAFR." (PMID 25261977, 2014). "The expression of EGFR and PAFR in CAOV-3 and SKOV-3 ovarian cancer cell lines was measured by Western blot and immunocytochemistry." (PMID 24886678, 2014). "This is the first study to examine the role of EGF, a mitogenic agonist that binds to EGFR, a tyrosine kinase receptor, on PAF production in ovarian cancer cells." (PMID 24721622, 2014). "PAK4 overexpression has been shown to promote ovarian cancer cell migration and invasion in a c-Src and MEK-1 kinase-dependent manner, and induce cell proliferation through the Pak4/c-Src/EGFR (epidermal growth factor receptor) pathway." (PMID 27919028, 2014). "Our data show that PAF increases EGFR phosphorylation through PAFR in a time- and dose- dependent manner in SKOV-3 ovarian cancer cells." (PMID 25261977, 2014). "In this study, we evaluated for the first time the antitumor effects of PAFR and EGFR targeting strategies in ovarian cancer cell lines using the PAFR antagonist WEB2086 and EGFR inhibitor AG1478." (PMID 24886678, 2014). "For example, CDKN2B and CDK4 as well as EGFR and NF1 are involved in the RB and RTK signaling pathways, respectively and the CCNE1, MYC and RAD52 module in ovarian carcinoma is involved in cell cycle." (PMID 24565034, 2013). "Additionally, the low frequency of KRAS mutation or BRAF mutations in type II ovarian carcinomas in the current and previous studies suggest that p-ERK expression may be affected by the other receptor tyrosine kinase regulation mechanisms (i.e., EGFR, Her2, etc.)." (PMID 23820584, 2013). "Five ovarian cancer cell lines (A2780, IGROV-1, OVCAR-3, OVCAR-4 and SKOV-3) with different EGFR-expression were used as target cells for natural and antibody-dependent cellular cytotoxicity assays." (PMID 23036052, 2012). "As with some other ovarian cancer biomarkers, CA125/MUC16 expressing cells signaling enhance epidermal growth factor receptor (EGFR) activation, which results in increasing its downstream effectors Akt and ERK1/2 and in enhanced MMP-2 and MMP-9 expression." (PMID 23319948, 2012). "Therefore, inhibiting EGFR could be one potential approach to treat ovarian cancer." (PMID 22952709, 2012). "Inhibition of phosphorylation of EGFR and AKT were confirmed in SKOV-3 and OVCAR-3 ovarian cancer cells by western blotting." (PMID 22952709, 2012).